CXCL8 (C-X-C motif chemokine ligand 8)
Diseases named in the same sentence as CXCL8 in open-access papers (continued):
Sharing a sentence is not in itself a finding about the gene and the disease.
thyroid cancer (continued). "Taken together, in vitro and in vivo data provide evidence for an action of CXCL8 as tumor-promoting agent and indicate that lowering CXCL8 levels in thyroid cancer microenvironment could be of therapeutic benefits." (PMID 29977225, 2018). "It was hypothesized that CXCL8 would exert its active role in thyroid cancer progression by paracrine binding to CXCR1 and CXCR2 expressed on the surface of PTC cells." (PMID 29977225, 2018). "Indeed, while the administration of rh-CXCL8 promoted tumor spread and reduced mice survival, targeting CXCL8 by a neutralizing Ab dose dependently reduced the metastatic spread of thyroid cancer cells and prolonged mice survival." (PMID 29977225, 2018). "Thus, several agents were tested for their efficacy in inhibiting the secretion of CXCL8 in the thyroid cancer microenvironment." (PMID 29977225, 2018). "We hypothesized that targeting thyroid cancer cells using the selective CXCR2 receptor antagonist AZD5069 may reduce the CXCL8-mediated pro-tumorigenic effects (i.e. via inhibition of cell migration) and/or suppress the tumour cell ability to secrete CXCL8 endogenously." (PMID 38900374, 2025). "It was reported that the inactivation of AMPK prompted the growth and development of thyroid tumors, and the AMPK-activator (AICAR) could inhibit the basal and the TNF α-induced CXCL8 secretion, both in normal human thyroid cells and in thyroid cancer cell lines." (PMID 32733803, 2020). "The experiment results show that PLX4720 is able to inhibit the secretion of CXCL8 in BRAFV600E-mutated thyroid cancer cells, which indicated that at least some of the antitumor activities of PLX4720 could be exerted through lowering of CXCL8 in the thyroid cancer microenvironment." (PMID 31583243, 2019). "CXCL8 also plays a crucial role in the process of epithelial to mesenchymal transition (EMT), consequently promoting thyroid cancer cell migration to metastatic sites." (PMID 38900374, 2025). "Thyroid carcinoma cells secrete chemokines such as CCL2 and CXCL8 to recruit immunosuppressive cells (e.g., TAMs), creating an immune escape microenvironment." (PMID 40823082, 2025). "According to transcriptome sequencing, antitumor chemokine regulatory genes (CXCR3) were upregulated, and protumor chemokine regulatory genes (CCR3, CXCL1, CXCL2, CXCL3, CXCL8, and CXCR2) were downregulated after MWA in thyroid cancer." (PMID 38779358, 2024). "Histamine, IL-6, IL-1, TNF-α, and chemokines such as CXCL1/GRO-α, CXCL8/IL-8, and CXCL10/IP-10 are secreted from mast cells when thyroid cancer cells are activated." (PMID 36293435, 2022). "Vitamin D differently modulated the secretion of CCL2 and CXCL8, by significantly inhibiting the secretion of CCL2 in both thyroid cancer cell lines and inhibiting the secretion of CXCL8 only in TPC-1 (ANOVAs p < 0.05)." (PMID 35498406, 2022). "Previous in vitro and in vivo results showed that the reduction of CXCL8 and CCL2 secretion inhibits some of the pro-tumorigenic effects mediated by both these chemokines in thyroid cancer." (PMID 35498406, 2022). "In thyroid cancer, Visciano and colleagues showed that MCs promote EMT via CXCL8 production, leading to AKT phosphorylation and Slug expression by thyroid cancer cells." (PMID 33418996, 2021). "The results of the present study indicate that phenformin has different effects in thyroid cancer cell, in which it affects viability, and in NHT cells, in which it inhibits the secretion of CXCL8." (PMID 31741708, 2019). "Continuous cell lines obtained from ATCs and well-differentiated thyroid carcinomas (WDTCs) secrete different cytokines and chemokines, such as GRO-α, GM-CSF, IL-1α, IL-6, CXCL8/IL-8, monocyte chemotactic protein-1 (MCP-1), and TNF-α." (PMID 31500315, 2019). "In particular, the in vitro inhibition of Akt (a downstream mediator of CXCL8 action), prevented Slug accumulation (an important mediator of EMT and Stemness), eventually blocking EMT and stemness of thyroid cancer cells." (PMID 29977225, 2018).
thyroid cancer (continued). "At present, CCL2, CCL15, CCL20, CXCL1, CXCL8, CXCL12, and CXCL16 are the main chemokines showing a role in thyroid cancer." (PMID 29977225, 2018). "Incubation of mast cells with thyroid cancer cell-derived conditioned medium produced a strong upregulation of a set of selected cytokines (TNF-α, CXCL6, and CXCL8), which consistently induced EMT in thyroid cancer cells." (PMID 29977225, 2018). "In 8505-c and BHT101-5 human thyroid carcinoma anaplastic cell lines and TPC1 papillary cells, dl922-947 decreased C-X-C motif chemokine ligand 8 (CXCL8) promoter binding by p65." (PMID 30413032, 2018). "Aim of this study was to test the effect of IFNγ on the basal and TNFα-stimulated secretion of CXCL8 in TCP-1 and BCPAP thyroid cancer cell lines (harboring RET/PTC rearrangement and BRAF V600e mutation, resp)." (PMID 27555670, 2016). "The aim of the present study was to investigate if vitamin D could modulate both thyroid cancer cell migration and their ability to secrete CCL2 and CXCL8." (PMID 35498406, 2022). "MCs also produce a broad spectrum of chemokines (CXCL8/IL-8, CCL25/TECK, CXCL10/IP-10, CXCL1/GRO-α), interleukins (IL-6), and other molecules (TNF-α) that are involved in the epithelial-to-mesenchymal transition (EMT) activation of thyroid cancer cells." (PMID 34204889, 2021). "Indeed, in vitro and in vivo studies demonstrated that CXCL8 plays a crucial role in promoting epithelial-mesenchimal transition (EMT) and migration/metastatization of thyroid cancer cells." (PMID 30867499, 2019). "The finding that phenformin inhibits the CXCL8 secretion only in NHT but not in thyroid cancer cells should be briefly discussed." (PMID 31741708, 2019). "Before addressing the link between CXCL8 and thyroid cancer, we will briefly review current evidence demonstrating the crucial role of CXCL8 in human malignancies of non-thyroid origin." (PMID 29977225, 2018). "The same group of investigators showed that CXCL8, through an autocrine circuit mediated by the CXCR1 receptor, is involved in the formation of spheres, in their self-renewal and in the tumor-initiating ability of thyroid cancer stem cells." (PMID 29977225, 2018). "At variance with these results, metformin did not affect the TNF-α-stimulated secretion of CXCL8 in thyroid cancer cell lines harboring the RET/PTC rearrangement or the BRAF V600e mutation (TPC-1 and BCPAP cells, resp)." (PMID 27555670, 2016). "Among IFNs, IFNγ was identified as the most powerful inhibitor; however, its ability to reduce the secretion of CXCL8 in thyroid cancer cells was not investigated previously." (PMID 27555670, 2016). "Aim of the present study was thus to investigate whether IFNγ inhibits the basal and the TNF-α-stimulated secretion of CXCL8 in TCP-1 and BCPAP thyroid cancer cells." (PMID 27555670, 2016). "This is because on the one hand, it could secrete histamine, CXCL1/GRO-α and CXCL10/IP-10 to promote the proliferation of thyroid cancer cells, and on the other hand, it could initiate EMT by secreting TNF, IL-6 and CXCL8/IL-8, which were essential in EMT process." (PMID 36568979, 2022). "The aim of the present study was to investigate whether vitamin D (1,25-OH2 D3) exerts both direct (cell viability and migration) and indirect (modulation of the pro-tumorigenic chemokines and CXCL8 and/or CCL2 secretion) antitumor effects in TPC-1 and 8505C thyroid cancer cell lines." (PMID 35498406, 2022). "Furthermore, a recent study reported that MTF could inhibit the secretion of CXCL8 stimulated by tumor necrosis factor-α (TNF-α) in primary cultures of normal thyroid cells and differentiated thyroid cancer cells." (PMID 31379740, 2019). "In conclusion, the results of the present study indicate that IFNγ, among its pleiotropic effects, is also able to inhibit CXCL8 secretion and cell migration in BRAF V600e mutated BCPAP but not in TPC-1 thyroid cancer cell line bearing the RET/PTC rearrangement." (PMID 27555670, 2016).
thyroid cancer (continued). "The present study demonstrates that IFNγ inhibits the basal and TNFα-stimulated secretion of CXCL8 in BCPAP, but not in TPC-1 thyroid cancer cell lines." (PMID 27555670, 2016). "The hypothesis that vitamin D could affect the CXCL8 and/or CCL2 secretion was never tested in thyroid cancer." (PMID 35498406, 2022). "Similarly, designed studies showed that IFN-γ does reduce the basal and the TNFα-stimulated secretion of CXCL8 both in normal thyroid cells and in BCPAP cells, but not in the TPC-1 thyroid cancer cell line." (PMID 29977225, 2018).
co-infection (51 papers, 2010 to 2025). "While the co-infection of A. actinomycetemcomitans with La5 resulted in reduced levels of all mediators, the co-infection with Lr32 promoted reduced levels of CXCL-8 and GM-CSF but increased the production of IL-1β." (PMID 35602018, 2022). "GECs mono-infected with A. actinomycetemcomitans produced CXCL-8, GM-CSF, and IL-1β, and the co-infection with both probiotic strains altered this profile." (PMID 35602018, 2022). "Specifically, production of key proinflammatory cytokines (e.g., IL-1α and IL-1β), chemokines (e.g., CCL20 and CXCL8), and VEGFA was markedly downregulated during co-infection with either HCMV variant, reflecting the known synergistic interference between the two pathogens." (PMID 40980889, 2025). "In our study, the weak negative association between CXCL8 and the viral load identified in the co-infection may be related to the production of molecules in response to an Leishmania spp." (PMID 37999614, 2023). "Protein-protein interaction network analysis further delineated pathogen-specific hubs: inflammatory mediators (CXCL8, CCL20, IL6) in the E group, molecular chaperones (CCT5, RUVBL1/2) in the S group, and a distinctive IL6-FBL-centered network in co-infection." (PMID 40771952, 2025). "On the other hand, lower levels of MIG and CXCL8 were observed among NC compared to the HIV group, and higher levels of CCL5 in NC compared to the co-infection group." (PMID 37999614, 2023). "In contrast to the co-infection group, we found a weak positive correlation between CCL2 and CXCL8 (r = 0.21) in the HIV group." (PMID 37999614, 2023). "In our model, we found the effects of co-infection with PA and HRV16 on CXCL-8 to be similar to those of HRV infection alone." (PMID 35265536, 2022). "Co-infection of epithelial cells with RV and NTHi increased release of neutrophil chemoattractants, CCL20 and CXCL8/IL-8, compared to infection with either pathogen alone." (PMID 35386999, 2021). "QPCR analysis showed that the expression trend of 10 genes between the co-infection and control groups (IL-17C, NFκB, AP1, C/EBPβ, CXCL1, CXCL8, MMP1, MMP3, GM-CSF, and MUC5AC) was consistent with the RNA-seq results." (PMID 31803158, 2019). "Our findings unveiled a weak negative correlation between the CXCL8 levels and viral load (r = −0.34) within the co-infection group." (PMID 37999614, 2023). "Furthermore, higher connectivity was observed among the chemokines, and a weak negative correlation between CXCL8 and the viral load in the co-infection group." (PMID 37999614, 2023). "Consistent with the present findings that showed that co-infection with Giardia attenuated C. rodentium-induced colonic elevation of MPO, a well-known marker of granulocyte infiltration, recent findings have reported that Giardia was able to cleave CXCL-8, a potent chemoattractant for neutrophils." (PMID 28622393, 2017).
atopic dermatitis (50 papers, 2009 to 2025). "Given the established role of the chemokine CXCL8 in driving neutrophil recruitment and exacerbating inflammation in atopic dermatitis, this specific reduction provides a possible molecular basis for the observed clinical relief in this case." (PMID 41516055, 2025). "Th17 cytokine (IL-17 and IL-22) upregulates the expression of CXCL8 and IL-6 in the skin of atopic dermatitis patients and promotes inflammation of the skin." (PMID 28558005, 2017). "As IL-8/CXCL8 concentrations are affected by infectious organisms, including Malassezia and bacterial agents, infectious organisms should be excluded when studying IL-8 as a biomarker of atopic dermatitis." (PMID 38464701, 2024). "Similarly, significantly increased IL-8/CXCL8 concentrations have been reported in previous studies that analyzed cytokines by swabbing the cerumen or occlusal surface of dogs with atopic dermatitis." (PMID 38464701, 2024). "CXCL8 is a proinflammatory chemokine and plays a role in the early accumulation of leukocytes, especially neutrophils, in the skin and is, therefore, an important part of the delayed type of hypersensitivity reaction, i.e., allergic dermatitis." (PMID 34086734, 2021). "This aligns with previous studies demonstrating that IL-37b can inhibit the in vitro induction of pro-inflammatory cytokines (IL-6 and TNF-α) and chemokines (CXCL8, CCL2, and CCL5) related to atopic dermatitis." (PMID 40444012, 2025). "In addition, it is necessary to determine whether IL6, CXCL8, and CCL2 levels are upregulated in dogs with atopic dermatitis and whether the symptoms of atopic dermatitis are alleviated when these cytokines are controlled." (PMID 39852930, 2025).
liver cancer (50 papers, 2013 to 2026). An epithelial or non-epithelial malignant neoplasm that arises from the liver. "High macrophage and neutrophil infiltration and CXCL8 expression were associated with poor prognosis in the TCGA liver cancer dataset." (PMID 36403057, 2022). "The purpose of the present study was to determine CXCL8 expression in a commercial human liver tissue microarray, and elucidate the effects and underlying mechanisms by which CXCL8 is involved in the malignant progression of human liver cancer." (PMID 32766720, 2020). "In the current research, we evaluated whether CXCL8, a member of CXC chemokines, was constitutively expressed in the tissues with liver cancer, and explored the underlying role and mechanism of CXCL8 in regulating malignant progression of liver cancer." (PMID 32766720, 2020). "In the current investigation, we found that CXCL8 was significantly up-regulated in tissues with liver cancer, and its overexpression was closely correlated with high clinical stage and tumor infiltration." (PMID 32766720, 2020). "The results from immunohistochemistry assay showed that the expression of CXCL8 at protein level was markedly increased in liver cancer tissues, whereas normal liver tissue showed a decreased expression of CXCL8 protein (P=0.0246)." (PMID 32766720, 2020). "By analyzing their relationship with the prognosis of liver cancer, we found the highly expressed CXCL8 and CXCL1 are related to the prognosis of liver cancer." (PMID 32730361, 2020). "The role of CXCL8 has been described extensively in the development and progression of liver cancers, mediating the recruitment of neutrophils to the tumor site and favoring tumor invasion, for instance, via secretion of matrix metalloproteinases, thus indicating poor prognosis." (PMID 36982370, 2023). "In addition, statistical analysis form liver cancer tissues demonstrated that up-regulated level of CXCL8 was positively concerned with high clinical stage and tumor infiltration (P=0.0061)." (PMID 32766720, 2020). "CXCL8 or CXCL1 may offer effective approaches for the development of targeted molecular therapeutics for liver cancer." (PMID 32730361, 2020). "We showed that CXCL8 expression was up-regulated in tissues with liver cancer, exogenous administration and overexpression of CXCL8 significantly facilitated to the malignant phenotypes of HepG2 cells by regulating tumor-specific protein expression including ERK1/2, survivin, caspase-3 and BAX." (PMID 32766720, 2020). "Moreover, CXCL8 or CXCL1 inhibition warrants further investigation as a candidate therapeutic target in liver cancer." (PMID 32730361, 2020). "It is markedly down-regulated in AH and liver cancer, whereas hepatic production and serum CXCL1 and CXCL8 are highly elevated and correlated AH severity in humans." (PMID 39619227, 2023). "Univariate and multivariate Cox regression analyses showed that the expression of CTSV, CXCL8, MKI67 and PRF1 were independent prognostic factors in liver cancer patients." (PMID 35902905, 2022). "The results showed that CCL2, CCR2, CXCL8, and CXCR2 were more highly expressed in adjacent normal tissues than in liver cancer tissues." (PMID 36403057, 2022). "The association between the expression of genes in the CCL2/CCR2 and CXCL8/CXCR2 axes and patient OS in the TCGA liver cancer dataset was analyzed." (PMID 36403057, 2022). "To further confirm these results, we compared the expression levels of the CCL2/CCR2 and CXCL8/CXCR2 genes in HCC tumors and adjacent normal tissues using data from the TCGA liver cancer database." (PMID 36403057, 2022). "Our data showed that high level expression of CXCL8 in tissues with liver cancer was identified as compared with non-cancer tissues, and its up-regulation was closely associated with clinical stage and tumor infiltration." (PMID 32766720, 2020). "We also propose that CXCL8 and CXCL1 may be a potential therapeutic target for liver cancer treatment." (PMID 32730361, 2020).
liver cancer (continued). "In addition, we could observe positive correlations of the expression levels of GOLGB1 or SF3B3 with the expression levels of CXCL8 and SOX4 in the liver cancer data of TCGA, implying the potential connection between them." (PMID 28038442, 2017). "However, it is not clear whether CXCL8 stimulates the malignant process of liver cancer." (PMID 32766720, 2020).